CTLA4 (cytotoxic T-lymphocyte associated protein 4)
Diseases named in the same sentence as CTLA4 in open-access papers (continued):
Sharing a sentence is not in itself a finding about the gene and the disease.
tumor (continued). "Following the success of monoclonal antibodies in the treatment of a variety of tumor diseases, current research is focused on identifying mABs to inhibit additional ICP axes besides the PD1-PD-L1 and CTLA4 axes and optimizing all of these therapies." (PMID 41228255, 2025). "The role of CTLA-4 in TREG function is of relevance to cancer immunotherapy, where inhibiting TREGs has been shown to improve anti-tumour immune responses and prognosis both in animal models and in clinical studies." (PMID 40265076, 2025). "By combining anti-PD-1 with anti-LAG3/CTLA4/TREM2, up to 100% tumor eradication was achieved in MMRd CRC and remarkably, in >70% in MMRp CRC." (PMID 40027748, 2025). "Engineered strains that express l-arginine, PD-L1, CTLA-4 nanobodies, or STING agonists have demonstrated significant efficacy in inducing immune-mediated tumor control in preclinical studies and are progressing toward clinical trials." (PMID 40264971, 2025). "Most studies indicate that PD-1/PD-L1 on T cells, CTLA-4 on Tregs, and CD47/signal regulatory protein-α (SIRPa) impede anti-tumor immunity." (PMID 40688079, 2025). "Beyond the PD-1/PD-L1 axis, other immune checkpoints, such as TIM-3, CTLA-4, and LAG-3, have gained significant attention for their roles in tumor immunology." (PMID 40870970, 2025). "By upregulating the expression of immunological checkpoint molecules such as PD-L1, CTLA-4, VISTA, Gal-9, and CD155, MDSCs impede tumor-infiltrating CD8+ T-cell-mediated anti-tumor immunity." (PMID 40097979, 2025). "Adding CTLA-4-blocking antibodies during TIL culture from ovarian tumors enhances CD8 + T-cell expansion and anti-tumor potency, improving TIL-based adoptive cell therapy outcomes." (PMID 41029427, 2025). "Studies have analyzed tumor tissues from mouse models of B-cell lymphomas and human cases of condylomatous and follicular lymphomas, revealing high expression of OX40 and CTLA-4 on the surface of tumor-specific Tregs (CD4+, Foxp3+)." (PMID 40356928, 2025). "Furthermore, in vivo studies showed that the NP vaccine could elicit a strong, antigen-specific CTL response against 4T1 TNBC cells and that combined treatment with a CTLA-4-siRNA-containing NLE could significantly enhance the anti-tumor immune response compared to the vaccine or CTLA-4-siRNA alone." (PMID 40943370, 2025). "Once bound, aptamers can deliver immune-modulating substances (e.g., IL-2, anti-CTLA-4, anti-PD-L1, anti-PD-1, IFN-α) directly to the tumor site, including cytokines, chemotherapeutic agents, and immune checkpoint inhibitors." (PMID 40870970, 2025). "Flow cytometry analysis further confirmed that CCR8+ Tregs highly express FOXP3 and CD25, along with immunosuppressive molecules such as CTLA4 and CD39, supporting their role as strongly suppressive tumor-localized Tregs." (PMID 41323783, 2025). "In the tumor microenvironment, CTLA-4 is predominantly expressed in Treg cells, with some effector T cells also expressing CTLA-4." (PMID 39915447, 2025). "Tremelimumab, targeting CTLA-4, especially in patients with HCV-related HCC, has demonstrated immunologic and clinical activity by enhancing tumor-specific T cell activation and intratumoral CD8+ infiltration." (PMID 40843361, 2025). "Distant tumour growth from SDT treatment was partially inhibited; however, MoOx-triggered SDT plus anti-CTLA-4 significantly decreased distant tumour growth." (PMID 39537767, 2025). "Performing bivariable Cox regression analyses, CTLA4 remained a significant predictor for DSS after controlling for age at diagnosis, tumor size, tumor grade, estrogen receptor expression, and Prosigna risk of recurrence (ROR) score." (PMID 40523912, 2025). "The in vitro CD8+ T cell activation, in vivo tumor suppression, tumor immune regulation, biodistribution, and adverse effects of PD1/CTLA‐4 BsAb were assessed and compared to free mixed monoclonal antibodies (aPD1 + aCTLA‐4)." (PMID 39606809, 2025).
tumor (continued). "Additional interactions with CTLA4, LAG3, LGALS9, and CD4 placed PD-1 at the center of a dynamic immunoregulatory network critical for tumor immune evasion." (PMID 40927719, 2025). "In contrast to αKO tumor sections, p-αKO tumors displayed markedly elevated cell counts positive for PD1, CTLA4, and LAG3." (PMID 40067762, 2025). "Several transcripts associated with immunological checkpoints, such as SIGLEC15, PDCD1LG2 (PD-L2), TIGIT, PDCD1 (PD-1), CD274 (PD-L1), CTLA4, LAG3, and HAVCR2 (TIM3), play a crucial role in tumor immune evasion." (PMID 40893939, 2025). "Tumor cells, along with other components of the TME, often express ligands for these checkpoints: CD80 for CTLA-4 and PD-L1 for PD-1, which helps tumors evade the immune system by suppressing T cell-mediated antitumor activity." (PMID 41007114, 2025). "CD96, CTLA-4, and PDCD-1 are important immune checkpoint proteins that play a crucial role in tumor immune evasion." (PMID 40746529, 2025). "Strategies, such as ICIs targeting CTLA-4, PD-1, and PD-L1, as well as CAR-T cell therapy, aim to reprogram the immune system to better recognize and eliminate tumor cells." (PMID 40242775, 2025). "Immunotherapy involves the use of immune checkpoint inhibitors (ICIs) to specifically block immune checkpoints such as PD-L1, CTLA-4, and CD47, thereby disrupting the immunosuppressive tumor microenvironment." (PMID 40547026, 2025). "Investigation of the tumor microenvironment (TME) revealed that melanoma patients responding to the combination of ICPi against PD1 and CTLA-4 had an enhanced frequency of CD45RO+ EOMES+ T cells with an effector memory, but not terminally exhausted phenotype." (PMID 40598271, 2025). "Anti-CTLA-4 antibodies can induce the upregulation of indoleamine 2,3-dioxygenase (IDO) expression in some HCC tumor cells, especially the IDO1 subtype." (PMID 41514551, 2025). "Based upon our observations, we next investigated the impact of targeting T cell checkpoints on tumor growth by using anti-TIM3, anti-TIGIT, anti-LAG3, or anti-CTLA4, alone or in combination with anti-PD-1." (PMID 40027748, 2025). "Bavunalimab is a CTLA-4- and LAG3-targeting bispecific antibody developed to achieve anti-tumor effects by activating T cells." (PMID 41155207, 2025). "Clinical trials with ICIs that target PD-1, PD-L1, and CTLA-4 have yielded exceptional results in recent years in certain types of neoplasia, which led experts at the FDA to approve the first ICI, the CTLA-4 inhibitor (Ipilimumab), in 2011." (PMID 40574027, 2025). "As a result, inhibitory immune pathways and checkpoint molecules—such as PD-1, CTLA-4, TIM-3, and LAG-3—are often highly expressed on tumor-infiltrating lymphocytes, which further supports the development of an immunosuppressive tumor landscape." (PMID 41294877, 2025). "Anti-PD-L1 plus anti-CTLA4 early response in HNSCC is characterized by CD4+ T cell activation and recruitment from tumor-draining lymph nodes." (PMID 40661938, 2025). "Along these lines, anti-CTLA4 ICB therapy has been shown to increase T cell motility and enhance therapeutic efficacy by disrupting the stable interactions between T cells and tumor or myeloid cells." (PMID 41050935, 2025). "The TGF-βR inhibitor enhanced tumor-infiltrating T cells, increasing CRC sensitivity to KN046, a drug that blocks both PD-L1 and CTLA-4." (PMID 39911388, 2025). "Early after the initiation of anti-PD-1 or anti-CTLA-4 therapy, effector T-cell activation and GZB release are reported to begin within 3–5 days, preceding observable tumor shrinkage." (PMID 41011180, 2025). "In MMRd tumors, resistance following anti-PD-1 treatment is driven by the expression of TIM3, LAG3, CTLA4, and TIGIT by TILs, as well as tumor clonal selection and the expression of TREM2, CSF1R, IFITM, TMEM176B and IL1B by myeloid cells." (PMID 40027748, 2025).
tumor (continued). "We also investigated the impact of targeting myeloid cell checkpoints together with T cell checkpoints on tumor growth by using anti-IL1B, anti-TREM2 or anti-IFITM, alone or in combination with anti-PD-1/CTLA4/LAG3." (PMID 40027748, 2025). "Tumor cells and stromal cells within NMIBC overexpress immune checkpoint molecules such as PD-L1 and CTLA-4." (PMID 40227644, 2025). "A latest study revealed that for microsatellite-stable colorectal cancer liver metastases—a typical type of “cold tumor”—the combined use of LIGHT cytokine and anti-CTLA-4 antibody can synergistically remodel the TME." (PMID 41346580, 2025). "Pathways such as PD-1/PD-L1, CTLA-4, and LAG-3 suppress T cell function and enable immune escape, ultimately accelerating tumor progression and dissemination." (PMID 40808954, 2025). "Meanwhile, dysfunctional CD8+ T effector cells characterized by high expression of cytotoxic markers (GZMK) and exhausted markers (PD-1, CTLA4, LAG3, and TIGIT) are significantly enriched in the peritumoral stroma and tumor tissues of HGSOC patients with HRD." (PMID 40830526, 2025). "Furthermore, in a preclinical study, botensilimab, an Fc-enhanced anti-CTLA-4 antibody, exhibited effectiveness comparable to or superior to conventional chemotherapeutics, such as gemcitabine, nab-paclitaxel, and cisplatin, controlling 7 of 10 tumor cells in combination with chemotherapy." (PMID 40075563, 2025). "For the immune part, we focused on the TCR-mediated signaling pathway and major immune checkpoints including PD-1, PD-L1, CD28, CD80/CD86, LAG3, CTLA4, TIGIT, CD155, OX40, OX40L, 4-1BB, and 4-1BBL (expressed on T cells, tumor cells, or APCs)." (PMID 40276607, 2025). "The combination group induced significantly more tumor-infiltrating CD8+ T cells than the vaccine and CTLA-4 siRNA-containing NLE groups." (PMID 40943370, 2025). "A recent report described a treatment-naïve GBM patient receiving immune checkpoint inhibitors (anti-PD-1, anti-CTLA-4, anti-LAG3) prior to surgical resection, resulting in prolonged disease-free survival and enhanced tumor-infiltrating lymphocyte activation." (PMID 41374974, 2025). "Activated NK cells express various T-cell immune checkpoint molecules like PD-1, CTLA-4, LAG3, and TIM3, which can inhibit their tumor-fighting functions." (PMID 41425568, 2025). "Depleting TREGs within the TME is, therefore, of importance, and targeting CTLA-4 antibody either to block CTLA-4 function or to actively target and deplete TREGs represent valid strategies for inducing potent anti-tumour activity." (PMID 40265076, 2025). "Taken together, these observations of expansion of several immune cells in TME post 225Ac-anti-CCR8 RIT align with the decreased tumor growth observed after 225Ac-anti-CCR8 and CTLA-4 immunotherapy combination treatment." (PMID 41035646, 2025). "Preclinical studies support this approach; for instance, co-inhibition of immune checkpoints such as PD-1, CTLA-4, and TIM-3 alongside CAR T-cell therapy has demonstrated improved tumor control and prolonged survival in the murine and canine models." (PMID 40867165, 2025). "Treg cells further dampen immunity by expressing CD25 and cytotoxic T lymphocyte protein 4 (CTLA4), releasing cytokines like TGFβ and IL-10, and consuming lipids and glucose, all of which impair tumor-killing T cells." (PMID 40741546, 2025). "To date, the U.S. Food and Drug Administration has approved three classes of ICIs, targeting CTLA-4, PD-1/PD-L1, and LAG-3, with additional agents in development across over 20 tumor types in the neoadjuvant, adjuvant, and metastatic settings." (PMID 41228374, 2025). "CT26-mock or CT26-ULBP2 tumor cells were subcutaneously transplanted into syngeneic BALB/c mice, which were then treated with either an isotype control antibody or anti-CTLA-4 antibody." (PMID 40558520, 2025).
tumor (continued). "The number of Tregs (FOXP3+, CD25high) and the expression of CTLA-4/CD39 correlate with immunosuppression and diminished responsiveness to immune checkpoint inhibitors across various tumor types." (PMID 41465319, 2025). "Mechanisms influencing DC antigen presentation: Tregs express cytotoxic T-cell antigen 4 (CTLA-4), affecting tumor surface antigen maturation, and immature anti-CTLA-induced T cells fail to recognize tumor surface antigens, leading to tumor cell immune escape." (PMID 40216744, 2025). "Tumor immune checkpoints (TICs) such as PDCD1 (PD-1), CTLA4, IDO1, and CD40 are critical regulators of immune responses and have emerged as promising therapeutic targets in cancer immunotherapy." (PMID 40918116, 2025). "Most of the CD8+ T cells in the tumor were CD45RAloCD27hi and expressed PD-1, TIM-3, CTLA-4, LAG-3, TIGIT, and CD39." (PMID 39273452, 2024). "CTLA4 is predominantly expressed on the surface of regulatory T cells and activated CD8+ T cells, and EVs in the tumor microenvironment further upregulate its expression to create an inhibitory milieu." (PMID 39528800, 2024). "The FDA-approved ipilimumab, a CTLA-4 blocking antibody, has shown success in various malignancies by targeting the PD-1 pathway, highlighting the significance of the B7-CD28 family in tumor immunotherapy." (PMID 39104717, 2024). "The tumor grew substantially slower than SCCVII model, and the therapeutic effect of single CTLA‐4 or anti‐PD‐1 antibodies was substantial." (PMID 38686626, 2024). "Recent studies have found that the CCR4 antagonist can enhance anti-tumour immune activity by reducing Tregs aggregation in the TME, and the combination of CCR4 inhibitor and CTLA-4 has a more significant effect." (PMID 38475858, 2024). "Bavunalimab (XmAb841 or XmAb22841) is a bispecific anti-CTLA-4/LAG-3 antibody, which activated T cells in NSG mice to achieve anti-tumor effects." (PMID 39252941, 2024). "Dual immune check point blockage by anti-CTLA-4 and anti-PD1 in syngeneic mice with NB tumors, resulted in tumor regression and improved OS, which was attributed to increased levels of T cells, NK cells, and inflammatory macrophages." (PMID 39294470, 2024). "Altogether, these findings indicate that while mice treated with anti-CTLA-4, alone or in combination with anti-PD-1, display the most dramatic increase in IFN-γ-producing Th1-like CD4 T cells within the tumor, anti-PD-1 also incites IFN-γ+ CD4 T cells." (PMID 38187708, 2024). "Remarkably, the blockade of CTLA4 or NKG2A by AYA22T-R2-13 augmented human CD8 T cell- and NK cell-mediated tumor cell lysis in vitro." (PMID 38473398, 2024). "Meanwhile, several important ICP genes, such as CD274, CTLA4, CD276, etc. were highly expressed in the PS1 and PS2 subtypes, indicating an immunosuppressive tumor microenvironment in these patients, and they were more likely to be benefit from ICIs." (PMID 38672082, 2024). "Tumor-bearing mice received an IFN-γ–neutralizing antibody in addition to combination therapy of IVAX and CTLA-4 blockade." (PMID 38517331, 2024). "Several studies have demonstrated that the combination of STAT inhibitors with radiotherapy, chemotherapy, anti-CTLA-4 and anti-PD-L1 ICIs, and anti-EGFR therapies like cetuximab can improve tumour response and ameliorate resistance." (PMID 38474047, 2024). "Anti-PD-1/PD-L1 and anti-CTLA-4 antibodies, along with targeted drugs like anti-EGFR and anti-VEGF, are being studied to boost T cell activation and anti-tumor immunity." (PMID 39731596, 2024). "The intricate involvement of the CTLA-4 and PD-1/PD-L1 pathways in HCC underscores their essential roles in regulating immune responses and significantly impacting tumor development." (PMID 39502703, 2024). "Focusing on tumor microenvironment (TME), CTLA-4, PD-1, and LAG-3 are expressed by immune cells, whereas PD-L1 is expressed by tumor cells." (PMID 38927526, 2024).
tumor (continued). "They evaluated the effectiveness of the combination of CTLA4 and RANKL inhibitors by analyzing tumor growth, tumor-infiltrating lymphocytes, and metastasis in mouse models." (PMID 38418707, 2024). "Hypoxia reduction sensitizes the tumors to CTLA-4/PD-1 checkpoint blockade as demonstrated by a robust increase in CD8+ T-cell effector function and tumor rejection." (PMID 39629128, 2024). "Tissue samples obtained from responders undergoing anti–CTLA-4 and anti–PD-1 therapy exhibited decreased levels of IGF2 expression within the mammary T11 tumor in comparison with the control group." (PMID 39545420, 2024). "In this study, a computational biology approach was employed to engineer a series of enriched aptamers targeting CTLA-4 and NKG2A receptors on CD8+ T cells and NKG2A receptors on NK cells interactions with B7-1/B7-2 and HLA-E on tumor cells." (PMID 38473398, 2024). "Moreover, the disruption of the intestinal barrier function by anti-CTLA4 treatment was found to be vital for the systemic translocation of adenosine derived from Bifidobacterium, consequently promoting Th1 activation and anti-tumor immunity via T cell-specific A2AR signaling." (PMID 38617537, 2024). "Flow cytometry was performed to confirm the MS results on several critical markers of tumor immune responses including CD25 (IL2RA), CD5, CD137 (TNFRSF9), ICOS, PD1 (PDCD1), CTLA4, and CD62L (SELL)." (PMID 38242867, 2024). "Our findings highlight that this CTLA4/NKG2A dual-functional aptamer enhances the immune response of human CTLs (CD8+ T cells) and NK cells against human tumor cell lines." (PMID 38473398, 2024). "This implies that immunological checkpoints such as CTLA-4 are upregulated when CHL progresses, potentially aiding tumour cells in immune evasion and enabling them to multiply and spread with reduced immune system interference." (PMID 38978137, 2024). "The reported findings revealed that OVs expressing PD-1 inhibitors synergistically acted with anti-CTLA-4 or anti-TIM-3 agents to potentiate the immune response in vivo and consequently achieve tumor control." (PMID 39055561, 2024). "Mice given oral supplementation of the microbial metabolite DAT show enhanced anti-CTLA-4 or anti-PD-1 ICI immunotherapy and delayed tumor development." (PMID 39351241, 2024). "Given the success of combination anti-PD-1 and anti-CTLA-4 ICB across diverse cancers, there is great interest in defining tumor-agnostic pretreatment biomarkers, including through using gut microbial abundance signatures." (PMID 38429524, 2024). "CTLA4 is upregulated in activated regulatory T cells (Tregs) and can bind to CD80 or CD86 on the surface of antigen-presenting cells, thus “shutting down” tumor immunity." (PMID 39091494, 2024). "We found that CTLA4 was highly expressed in tumor tissues and LAG3 was lowly expressed in tumor tissues." (PMID 38604154, 2024). "Another preclinical study with triple CTLA4, PD-1, and PI3K blockade reshaped the tumor microenvironment, enhancing T-cell–mediated tumor regression." (PMID 39271499, 2024). "Comparable results were obtained after combined hsBCL9z96 and anti-CTLA-4 treatment was administered to established CT26 tumor-bearing mice (TGI = 74.8%) and to established MC38 tumor-bearing mice (TGI = 78.4%)." (PMID 38811552, 2024). "Metastatic melanoma is the most responsive tumor type for ICT, with about 17% responding to anti-PD-1 antibody, about 27% responding to anti-CTLA-4 antibody, and about 55% responding to their combined therapy." (PMID 39474427, 2024). "For example, inhibiting immune checkpoints such as PD-1, CTLA-4, and TIM-3, alongside CAR-T-cell therapy, have demonstrated increased treatment efficacy in a D270 mouse model, evidenced by better control of tumor growth and extended survival." (PMID 38727262, 2024). "CTLA-4 likely promotes new T cell priming in these models, given the observed increase in TCR diversity of tumor-infiltrating T cells." (PMID 38349740, 2024).